TNF (tumor necrosis factor)
Diseases named in the same sentence as TNF in open-access papers (continued):
Sharing a sentence is not in itself a finding about the gene and the disease.
tumor (continued). "If either TNFα or IFNγ signaling in tumor-infiltrating CD4+ T cells is absent upon antigen recognition, tumor progression is stimulated, whereas combined TNFα and IFNγ signaling in CD4+ T cells prevents tumor angiogenesis and tumor-cell proliferation." (PMID 32733461, 2020). "An increased proportion of CD8+ T cells in the initial TILs supplemented with anti-CTLA-4 antibody compared to non-supplemented TILs secreted TNF and IFN-γ and expressed CD107a upon co-culture with autologous tumor cell lines." (PMID 32127601, 2020). "RFA with intratumoural OK-432 injection resulted in distant tumour suppression, prolonged survival, and increased dendritic cells, cytotoxic T cells, IFN-γ, and TNF-α, whereas RFA or OK-432 alone did not produce this effect." (PMID 32541941, 2020). "TNF-α levels did not exhibit obvious differences in the tumours of MO mice compared to those of CTX-treated mice; however, TNF-α levels were obviously decreased in FLP-treated MO mice compared to those of CTX-treated mice (P < 0.05)." (PMID 32308722, 2020). "Therefore, the present work may explain the cancer-promoting effect of TNF-α/TNFR1 in that 9,40, upon TNF-α stimulation, cancer cell signaling pathways shift towards TNF-α/TNFR1-mediated anti-apoptotic signals owing to low HRG expression, and thus to pro-tumor progression and drug resistant states." (PMID 32929358, 2020). "About 70–80% of tumor-infiltrating CD8 T-cells did not express IFN-γ, TNFα or the degranulation marker CD107, with only a small subset (about 15%) producing only IFN-γ in ICPI and combination groups." (PMID 33207844, 2020). "Collectively, results suggest that M2 macrophages are activated in grade I tumour tissue although, due to the variability in the expression levels for IL-6, TGF-beta and TNF-alpha in individual samples, these results were not significant." (PMID 32070062, 2020). "Cytokine production assay also showed that, compared with controls (vehicle or no treatment), SLR14 treatment promoted tumor-infiltrating CD8+ T lymphocytes to produce much higher levels of IFNγ and TNFα." (PMID 31601678, 2019). "COX-2 is not expressed in the non-pathological colonic mucosa, while it is induced in the tumor microenvironment by pro-inflammatory stimuli such as bacterial lipopolysaccharides, IL-1β, IFN-γ and TNF-α." (PMID 31027294, 2019). "While we did not see any difference of TNF-α, IL-15, and IFN-γ secretion between the tumor and the adjacent healthy tissue, we showed a trend with a higher production of IL-6 in tumor." (PMID 31105699, 2019). "NK-differentiated MP2 tumors did not grow in hu-BLT mice, and when tumor differentiation was prevented by using antibodies to IFN-γ and TNF-α, tumors grew substantially." (PMID 31878338, 2019). "Ex vivo incubation of the tumor cells with lipopolysaccharide (LPS), but not GDC-0152, induced the majority of the immune cells to express TNFα." (PMID 31521127, 2019). "Moreover, CML derived MDSCs themselves have been suggested as a source of TNFα, tempting to speculate that TNFα inhibition could also impact on CML biology, not only by direct effects on the malignant stem cell itself but also by supporting a tumor promoting niche." (PMID 31272418, 2019). "In this report, intra-tumoral injection with STING ligand resulted in elevated levels of TNFα, IL6 and CCL2, but no significant increase in IFNγ within the Panc02 tumor microenvironment." (PMID 31036082, 2019). "Whilst our data clearly indicate that TNFα‐CSG can remove ECM components in advanced tumours, one limitation of this study is that the potential suppressive effect by TNFα‐CSG on tumour fibroblasts, and their secretion of ECM components was not addressed." (PMID 31709774, 2019). "To this end, we have analyzed the expression of CXCL8 in TNFα-stimulated and non-stimulated MDA-MB-231:MSC co-cultures in which Notch1 was down-regulated by siRNA in the tumor cells." (PMID 31105691, 2019).
tumor (continued). "Fluorescein‐labelled TNFα‐CSG, unlike TNFα, selectively homed to tumour matrix in vivo, in the same manner as free CSG peptide." (PMID 31709774, 2019). "Our data indicate that without TNFα stimulation, CXCL8 produced in TNBC:MSC co-cultures was released exclusively by the tumor cells and resulted from basal p65 activation in the tumor cells." (PMID 31105691, 2019). "In TMZ-receiving patients with GBM harboring wild-type IDH1 and non-G-CIMP, the combined expression of H2AFJ with PMT, TNFα-NF-κB, or IL6-STAT3 geneset exhibited an inverse correlation with time to new tumor event after the treatment." (PMID 31906036, 2019). "Therapeutically, TNFα‐CSG is highly effective by activating anti‐cancer T cells and suppresses tumour growth without systemic toxicity or increase in metastatic activity." (PMID 31709774, 2019). "Of note, non-suppressive tumor-infiltrating CD56bright ILCs were distinguished from regulatory CD56+ ILCs by a different gene expression profile and high production of IFNγ and TNFα in the absence of IL-22." (PMID 30454038, 2018). "TNF-α induced a significant increase in the percentage of cells expressing CCR6, both in TPC-1 and BCPAP tumor cell lines, but not in normal human thyroid cells." (PMID 29977225, 2018). "In the C15A3 tumour, the transfer of IL‐12‐producing CAR‐T cells but not the normal CAR‐T cells increases the number of macrophages that express TNF‐α in the tumours." (PMID 29963704, 2018). "We also preliminary attempted subcutaneous injection of B16F10 cells that we still found significantly increased tumor-infiltrating IFNγ and/or TNFα producing CD4 and CD8 T cells although tumor size was not reduced." (PMID 29403003, 2018). "Functional activity of the CAR was confirmed by demonstrating the ability of 4P28ζN+, but not 4PTrN+, T cells to elicit cytotoxicity and release of interferon (IFN)-γ and tumor necrosis factor (TNF)-α, when co-cultivated with PLP but not PL tumor cells." (PMID 29540684, 2018). "These tumor infiltrating Tregs exhibited the ability to produce IL-10, but not IFN-γ, TNF-α, or IL-17 and to inhibit the proliferation of responder CD8+ T cells." (PMID 29844297, 2018). "In addition, the ability of mint extracts to stimulate the production of MCP-1 and TNF-α has both a negative aspect, when we consider the impact on inflammatory diseases, and a beneficial aspect if we take into account the potential effect on the prevention of tumor development." (PMID 30563252, 2018). "For inflammatory markers (TNF-α, COX-2, and TGF-β) in tumor tissue, MD were non-significantly higher with stronger expression but the differences were very small." (PMID 30497427, 2018). "Although activating death receptors to attain tumor growth inhibition has been investigated, not much progress has been achieved owing to the toxic effects of death receptor ligands-FASL and TNF." (PMID 29263422, 2017). "In the present study, the levels of TNF-α, IL1-β and IL12p70 increased in both aged groups irrespective of parity, and decreased as a response to tumor spread only in the parous group, in a similar fashion as observed for the M2-type cytokines." (PMID 28966800, 2017). "It has been demonstrated that IVIg significantly hindered secretion of TNF-α, IL-12p40, and CCL2 after M1 macrophages were stimulated with LPS without, nonetheless, affecting their property to inhibit tumor growth." (PMID 28970834, 2017). "The concentrations of TNF-α and IL-6 in the APS group had no obvious difference from those in the NS group of the MyD88−/− tumor-bearing mice (P > 0.05)." (PMID 28303957, 2017). "In summary, APS induces the expressions of mRNAs and proteins of TLR4, TRAF-6, NF-κB and AP-1, as well as increasing the levels of TNF-α and IL-6 in the serum of the TLR4+/+ tumor-bearing mice, but not TLR4−/− tumor-bearing mice." (PMID 28303957, 2017). "We found that SLE altered the expressions of some genes related to tumor immune evasion (e.g. IL-6, IL-17, STAT1, TNF-α, CD45, MHCII) (Data not shown)." (PMID 28596565, 2017).
tumor (continued). "Our finding on the increase of serum TNFα and IL-6, but not IL-1β, in LLC tumor-bearing mice is similar to these patient data." (PMID 28536426, 2017). "This is not surprising, because the protein level of TNF-α is greatly elevated owing to induction of DSS in the CAC model, which deeply inhibits the expression of CDX2 in tumor cells and malignant transformed cells at the invasive front." (PMID 26910375, 2016). "Cisplatin treatment did not inhibit or induce the secretion of IL-10, TNF-α, IFN-γ and TGF-β in the C57BL/7 mice with miR-Sc-overexpressing tumours." (PMID 27147225, 2016). "Compared with the control group, TNFα or IFNγ slightly but not significantly suppressed tumor growth, while TCP-1/TNFα or TCP-1/IFNγ significantly decreased tumor size compared with their unconjugated counterparts." (PMID 27342639, 2016). "Antitumor “N1-like” cells generated in the absence of TGF-β produced higher levels of TNF-α, MIP-1α, H2O2, and NO and were cytotoxic to tumor cells both in vitro and in vivo." (PMID 26966341, 2016). "However intracellular cytokine staining of splenic CD4+ T cells from mice in which tumor escape had occurred indicated an increased rather than decreased proportion of IL-2+ T cells in the presence of tumor-specific B cells, with the majority of T cells co-expressing TNF." (PMID 27121060, 2016). "RMP16 inhibited proliferation of multiple tumor cells and vascular endothelial cell but not mammary non-tumorigenic epithelial cells, and bound TNFR by competitively displacing TNF α." (PMID 26337231, 2015). "However, we found no in vivo evidence for nuclear localization of ectopic WWOX in the presence of ectopic TNFα expression, indicating that the tumor suppressive functions may not be at the level of detection or alternatively they may be mediated through cytoplasmic WWOX functions." (PMID 26302329, 2015). "Take together, our findings clearly demonstrate serum IL-6 rather than IL-27, TNF-α, and VEGF playing a definite role in liver deterioration and tumor progression, as well as further affecting HCC patient survival." (PMID 25908103, 2015). "We observed that P1G10 inhibited angiogenesis measured by the decline of Hb and VEGF within the tumor, and TGF-β displayed a non-significant increase and TNF-α showed a minor non-significant reduction." (PMID 25826531, 2015). "As suggested by in vitro experiments, an anti-TNFα treatment, but not L-NAME treatment (an inhibitor of NO production), partially inhibited vaccination-induced tumor regression." (PMID 26337837, 2015). "When the relationship of TNF-α in the subcutaneous adipose tissue and TNF-β in the tumor was analyzed, no statistical significance was found for CC (p = 0.0892)." (PMID 26732354, 2015). "Tumor resistance to NK cell-mediated killing induced by IL-2 + anti-CD16mAb + sAJ2-treated NK cells is induced by combination of IFN-γ and TNF-α since antibodies to both, and not each cytokine alone, were able to restore tumor sensitivity to NK cells." (PMID 26697005, 2015). "Reduced T cell-NF-κB activity did not reduce expansion of tumor-specific T cells, but resulted in decreased production of tumor antigen-specific IFN-γ and TNF-α, as well as diminished cytotoxicity against tumor antigen-expressing cells in vivo." (PMID 25648675, 2015). "In our study, we observed a high level of proinflammatory cytokines, such as TNF-α, IFN-γ and IL-12 in sera from SZU-101-treated tumour-bearing mice, while no induction of TH-2 cytokines IL-4, IL-5 or IL-10 was detected." (PMID 25887995, 2015). "Th1 polarization was demonstrated after stimulation with CTA-pulsed DCs and co-culture with tumor cells, by detecting more than 50-fold increase in IFN-γ and TNF-α production and no significant change in IL-4, IL-5, and IL-10 levels, using ELISA." (PMID 25739119, 2015). "Taken together, these latter datasets suggest that TNF induction is only consistently seen in response to ADT therapy, rather than as a consequence of tumor progression." (PMID 26327448, 2015).
tumor (continued). "Levels of proinflammatory cytokines IL-1β, IL-18, Tumor Necrosis Factor (TNF)-α and Interferon (IFN)-γ were decreased in the tumor microenvironment in the absence of inflammasome proteins." (PMID 25268644, 2014). "Their work does not directly implicate TNF-α, though, but instead found enhanced production of several proinflammatory cytokines, including TNF-α, in the tumour microenvironment during the development of cancer." (PMID 24734105, 2014). "During further experiments with combined SAHA and TNF-alpha (TNF-α) treatment, we noticed a rapid cytotoxic effect on our investigated tumor cells (data not shown)." (PMID 24618889, 2014). "Splenocytes of irradiated EL4-bearing C57/BL6 mice, but not those of irradiated non-tumor-bearing C57/BL6 mice, produced significant amounts of IFN-γ and TNF-α." (PMID 24686897, 2014). "In WT mice receiving Fab anti-CD200R, no tumor cells are detectable following immunotherapy, and CD4+ cells produced increased TNFα/IL-2/IFNγ on stimulation with EMT6 in vitro." (PMID 25409195, 2014). "When stimulated by tumor cells and an anti-CD3 antibody, Vγ1 T cells express IFN-γ and GM-CSF, but not IL-1β, TNF-α, IL-12, IL-2, IL-4, IL-10, or TGF-β." (PMID 25538706, 2014). "We found the PDA tumor cells to express CD29 (integrin β1), CD49f (integrin α6), and CD107a and b, the expression of which was not modulated by TNF." (PMID 24098720, 2013). "While our data speak for an immune mediated anti-tumorigenic effect of TNF via TNFR1, as cautionary result we also observed that the exogenous treatment of tumor-bearing mice with TNF augmented tumor growth rather than controlled it." (PMID 24098720, 2013). "In agreement with the expression pattern of the other pro-inflammatory NFκB target genes TNFα and IL-1β, we found that COX-2 levels were dramatically decreased with PDTC treatment in non-tumor bearing skin but not in tumors." (PMID 22761871, 2012). "While we show that the Mam-A2.4 specific CD8 T cells secreted more IFN-γ, TNF-α and Granzyme B compared to either the full-length or the other epitope Mam-A specific CD8 T cells, this adoptive T cell therapy failed to prevent tumor relapse." (PMID 22911764, 2012). "Paclitaxel has been shown to induce soluble tumor necrosis factor alpha (sTNF-α) production in macrophages, but the involvement of TNF production in taxane cytotoxicity or resistance in tumor cells has not been established." (PMID 22225778, 2012). "Although not induced themselves by DMXAA at the RNA level, NF-κB, TNF-α, IL-6 and IFN-β have several downstream targets that are differentially expressed between control and DMXAA-treated tumours." (PMID 22415295, 2012). "Both tumor-bearing groups (SE and EE housing) had increased resistin, IL-6, TNF-α, PAI-1 and MCP-1 levels irrespective of the different housing environment demonstrating higher inflammatory response due to the presence of the tumor." (PMID 23272114, 2012). "Tumor necrosis factor-alpha (TNF-alpha) secretion seems important for DMXAA action in vivo, since its anti-tumor activity was impaired, though not completely lost, in TNF-alpha receptor knock-out mice." (PMID 22848372, 2012). "We also showed that IL-22 did not enhance the anti-tumor immunity effectively in vivo by increasing the expression of IFN-α and TNF-α in A498 cell xenografts." (PMID 21625390, 2011). "Oppositely to TNF-α and VEGF, serum level of IL-6 was changed in tumor-bearing mice but it did not correlate with alterations in macrophage activity or other effects." (PMID 21760797, 2011). "However, it has been reported that Treg from tumor-bearing mice may impair the expression of DC costimulatory molecules CD80, CD86, and CD40, suppress DC production of proinflammatory cytokines IL-12 and TNF-α, and inhibit their ability to induce T-cell activation in vitro." (PMID 22110524, 2011).
tumor (continued). "Mouse bone-marrow-derived DCs first activated with the TLR4 ligand LPS and exposed to tumor-induced Treg maintain expression of CD80, CD86, and CD40, produce IL-12 or TNF-a, and are not impaired in their allostimulatory activity." (PMID 22110524, 2011). "CD8+ T cells rapidly up-regulate IFN-γ and TNFα expression upon activation, therefore, the locally produced IFN-γ and TNFα in the tumor microenvironment by tumor-infiltrating T cells should be non-toxic and yet effective sensitizers in TRAIL therapy." (PMID 21264227, 2011). "Although TNF secretion was mediated by Egr-1, TRAIL secretion only occurred in a tumour cells line that did not express functional Egr-1." (PMID 20087343, 2010). "In contrast, tumour cells secreted abundant MMP-3 and MMP-9 following TNF treatment, suggesting the use of nonredundant pathways by IL-17 and TNF." (PMID 19014637, 2008). "During our study we observed an increase of plasmatic TNF α in rats with NMU-induced and estradiol dependent tumours when compared to controls without NMU-induced tumours." (PMID 18045456, 2007). "The antitumour efficacy of IHP with melphalan with or without TNF-α was evaluated for the CC531, ROS-1 and BN-175 tumour starting at an equal size of 5–6 mm in diameter." (PMID 12610519, 2003). "Even in ROS-1 tumours, which are moderately sensitive to TNF-αin vitro, IHP with TNF-α alone showed no tumour response." (PMID 12610519, 2003). "In order to investigate this mechanism, melphalan concentrations were measured in tumour and liver tissues after IHP with melphalan with and without TNF-α." (PMID 12610519, 2003). "Secondly, in the patient where apoptosis was induced in tumour vessels following treatment with DMXAA, no TNF induction was detectable in tumour tissue or plasma." (PMID 12085190, 2002). "The generated CD4+ T cells secreted interferon (IFN)-gamma, tumour necrosis factor (TNF)-alpha, TNF-beta, and interleukin (IL)-6 (but not IL-4), and exhibited a high level of cytolytic activity against several tumour cell lines." (PMID 8554971, 1996). "4-1BB ligand (4-1BBL), a member of the TNFR/tumor necrosis factor (TNF) superfamily, is expressed on immune cells—including dendritic cells (DCs), B cells, macrophages, and T cells—and on non-lymphoid cells such as fibroblasts and tumor cells." (PMID 41541266, 2026). "Whereas tumor-responsive CD8+ T cells in the TIL products failed to produce cytokines, CD4+ T cells not only displayed increased PD1 expression ex vivo but also produced TNF in response to autologous tumor digest." (PMID 40897471, 2025). "In this tumor context, AMP did not directly inhibit tumor-cell proliferation but activated BMDMs, enhancing their phagocytic and migratory activity and increasing the production of TNF-α, IL-6, IFN-λ in BMDMs and in the serum of tumor-bearing mice." (PMID 41374013, 2025). "In the solid compared to the non-solid, TNF expressed in multiple immune cells (Treg, B, DC, CD8 T, CD4 T and macrophages) interacted with TNFRSF21 in epithelial cells which may enhance tumor cell survival and immune evasion 106,107." (PMID 39803458, 2025). "Moreover, recognition of autologous tumor digest by TIL induced the production of IFN-γ, TNF-α, and MIP-1β in comparison to TIL cultured without stimulus (TILs only)." (PMID 40806287, 2025). "Notably, none of these TNF-α–marker correlations were evident in the control group, underscoring that the TNF-α/tumor marker relationship is a malignancy-specific phenomenon and not a general feature of baseline physiology." (PMID 40299527, 2025). "IFN-γ was the critical mediator in this dormant tumor phenotype as neutralizing IFN-γ antibodies, but not antibodies to TNF-α, decreased CVCPos and increased Ki-67+ D2A1 cells in a coculture of CD103+DCs and CD8+ T cells from Tgfbr2MyeKO mice with CVC labeled D2A1 tumor cells (Supple fig." (PMID 40568095, 2025).